OR8B8 (olfactory receptor family 8 subfamily B member 8)
Description:
Odorant receptor (Potential). May be involved in taste perception.
Synonyms: TPCR85
Tractability: Antibody: UniProt places it where antibodies can reach, with high confidence; UniProt predicts a signal peptide or a membrane-spanning region; its Gene Ontology location is reachable by antibodies, with medium confidence.
Gene: Protein-coding gene on chromosome 11 (124,437,445 to 124,445,696, reverse strand). Ensembl gene ENSG00000197125.
Subcellular location: Cell membrane
Pathways (Reactome):
Sensory Perception: Expression and translocation of olfactory receptors
Gene Ontology:
Molecular function: olfactory receptor activity; G protein-coupled receptor activity
Biological process: G protein-coupled receptor signaling pathway; sensory perception of smell; detection of chemical stimulus involved in sensory perception of smell
Cellular component: membrane; plasma membrane
Genetic constraint (gnomAD): Loss-of-function variants: 9 observed, 12 expected, observed/expected ratio (o/e) 0.75, 90% interval 0.45 to 1.31. The upper end of that interval is the gene's LOEUF score, 1.31, which puts it in group 5 of 6, group 1 being the genes least tolerant of losing a copy. Missense variants: 390 observed, 400.2 expected, observed/expected ratio (o/e) 0.97, 90% interval 0.9 to 1.06. Synonymous variants: 150 observed, 153.2 expected, observed/expected ratio (o/e) 0.98, 90% interval 0.86 to 1.12.
Homologues: Orthologues: macaque OR8B8 (95% identical), rabbit OR8B8 (87% identical), mouse Or8b8 (86% identical), rat Or8b8 (86% identical), pig OR8B8 (85% identical). Paralogues in human: OR8B12 (80% identical), OR8B3 (72% identical), OR8B2 (71% identical), OR8B4 (67% identical), OR8G1 (64% identical), OR8G5 (64% identical), OR8G3 (61% identical), OR8D1 (60% identical), OR8A1 (59% identical), OR8D2 (58% identical), OR8D4 (58% identical), OR8G2P (58% identical), and 84 more.
Diseases named in the same sentence as OR8B8 in open-access papers:
OR8B8 is named in the same sentence as 1 disease in open-access papers, as found by Europe PMC text mining. Sharing a sentence is not in itself a finding about the gene and the disease. The quoted sentences say what the papers report.
tumor (1 paper, 2020). "For example, OR8B8 and OR8H1 were exclusively detected in malignant breast epithelial cells, whereas OR1A1 and OR2M3 activation were observed in 11 and 10 different tumor types respectively, suggesting a distinct mode of expression regulation." (PMID 32917933, 2020).